KEAP1 (kelch like ECH associated protein 1)
Description:
Substrate-specific adapter of a BCR (BTB-CUL3-RBX1) E3 ubiquitin ligase complex that regulates the response to oxidative stress by targeting NFE2L2/NRF2 for ubiquitination. KEAP1 acts as a key sensor of oxidative and electrophilic stress: in normal conditions, the BCR(KEAP1) complex mediates ubiquitination and degradation of NFE2L2/NRF2, a transcription factor regulating expression of many cytoprotective genes. In response to oxidative stress, different electrophile metabolites trigger non-enzymatic covalent modifications of highly reactive cysteine residues in KEAP1, leading to inactivate the ubiquitin ligase activity of the BCR(KEAP1) complex, promoting NFE2L2/NRF2 nuclear accumulation and expression of phase II detoxifying enzymes. In response to selective autophagy, KEAP1 is sequestered in inclusion bodies following its interaction with SQSTM1/p62, leading to inactivation of the BCR(KEAP1) complex and activation of NFE2L2/NRF2. The BCR(KEAP1) complex also mediates ubiquitination of SQSTM1/p62, increasing SQSTM1/p62 sequestering activity and degradation. The BCR(KEAP1) complex also targets BPTF and PGAM5 for ubiquitination and degradation by the proteasome.
Synonyms: INrf2; KIAA0132; KLHL19; MGC10630; MGC1114; MGC20887; MGC4407; MGC9454
Tractability: Small molecule: an approved drug acts on it; a structure with a bound ligand is known; a high-quality ligand is known; it has a high-quality binding pocket; it belongs to a druggable protein family. PROTAC: UniProt records ubiquitination sites on it; ubiquitination databases record sites on it; its protein half-life has been measured; a small molecule that binds it is known.
Chemical probes: KI-696 (high quality), ML334
Gene: Protein-coding gene on chromosome 19 (10,486,119 to 10,503,558, reverse strand). Ensembl gene ENSG00000079999.
Subcellular location: Cytoplasm; Nucleus
Subcellular location (Human Protein Atlas): Centriolar satellite; Nucleoplasm; Cytosol
Pathways (Reactome):
Cellular responses to stimuli: KEAP1-NFE2L2 pathway; Nuclear events mediated by NFE2L2
Metabolism of proteins: Neddylation; Ub-specific processing proteases
Disease: Potential therapeutics for SARS
Immune System: Antigen processing: Ubiquitination & Proteasome degradation
Gene Ontology:
Molecular function: protein binding; RNA polymerase II-specific DNA-binding transcription factor binding; transcription regulator inhibitor activity; ubiquitin-like ligase-substrate adaptor activity; disordered domain specific binding; identical protein binding
Biological process: cellular response to oxidative stress; negative regulation of response to oxidative stress; negative regulation of transcription by RNA polymerase II; proteasome-mediated ubiquitin-dependent protein catabolic process; protein ubiquitination; regulation of autophagy; ubiquitin-dependent protein catabolic process; positive regulation of proteasomal ubiquitin-dependent protein catabolic process
Cellular component: Cul3-RING ubiquitin ligase complex; cytoplasm; cytosol; inclusion body; midbody; nucleoplasm; nucleus; actin filament; endoplasmic reticulum; protein-containing complex
Genetic constraint (gnomAD): Loss-of-function variants: 26 observed, 60.6 expected, observed/expected ratio (o/e) 0.43, 90% interval 0.31 to 0.6. The upper end of that interval is the gene's LOEUF score, 0.6, which puts it in group 2 of 6, group 1 being the genes least tolerant of losing a copy. Missense variants: 539 observed, 890.09 expected, observed/expected ratio (o/e) 0.61, 90% interval 0.56 to 0.65. Synonymous variants: 350 observed, 365.78 expected, observed/expected ratio (o/e) 0.96, 90% interval 0.88 to 1.04.
Cancer hallmarks: escaping programmed cell death (suppresses)
Homologues: Orthologues: chimpanzee KEAP1 (100% identical), macaque KEAP1 (99% identical), pig KEAP1 (98% identical), dog KEAP1 (98% identical), mouse Keap1 (94% identical), rat Keap1 (94% identical), rabbit KEAP1 (89% identical), tropical clawed frog keap1 (75% identical), zebrafish keap1b (73% identical), guinea pig KEAP1 (63% identical). Paralogues in human: KLHL20 (35% identical), KLHL2 (35% identical), KLHL17 (35% identical), KLHL3 (34% identical), KLHL1 (34% identical), KLHL5 (34% identical), KLHL4 (33% identical), KLHL12 (32% identical), KLHL18 (31% identical), KLHL28 (31% identical), IPP (31% identical), KLHL8 (29% identical), and 42 more.
Diseases named in the same sentence as KEAP1 in open-access papers:
KEAP1 is named in the same sentence as 413 diseases in open-access papers, as found by Europe PMC text mining. Sharing a sentence is not in itself a finding about the gene and the disease. The quoted sentences say what the papers report.
lung carcinoma (339 papers, 2010 to 2026). "The CoQ–FSP1 axis was shown to mediate ferroptosis and radioresistance in KEAP1‐deficient lung cancer cells, further highlighting the close association between Nrf2 and cellular ferroptosis." (PMID 40919133, 2025). "Our analysis also provides indications that such combination therapy would be less effective in STK11-/KEAP1-mutated lung cancer and lung cancer of neuroendocrine lineage." (PMID 39995872, 2025). "Analysis of an additional immunotherapy cohort, the MSK lung cancer cohort, corroborated our findings, demonstrating that mutations in KEAP1 or STK11 were linked to unfavorable outcomes, as evidenced by significantly poorer OS." (PMID 41378285, 2025). "Typically, KEAP1 represses NRF2 transcription; however, in KEAP1-mutated lung cancer cells, the upregulation of NRF2 results in increased FSP1 expression, thereby facilitating ferroptosis induction." (PMID 39875356, 2025). "For instance, Nrf2 activation driven by KEAP1 mutations accelerates lung cancer progression while its inhibition can sensitize colorectal cancer cells to oxaliplatin-induced ferroptosis." (PMID 41212415, 2025). "Experimental studies in lung cancer mouse models demonstrate that KEAP1 or FBXO22 deficiency promotes metastatic spread through BACH1-mediated mechanisms." (PMID 40507333, 2025). "In murine models of lung carcinogenesis, we previously recognized that macrophages are associated with the immunosuppressive phenotype of KEAP1-mutant lung cancer." (PMID 41462606, 2025). "Although we discussed the Nrf2/Keap1 pathway, which is associated with GSH, in Section 3, various approaches to lung cancers have been addressed with respect to the modulation of the Nrf2 or Nrf2/Keap1 axis." (PMID 40722961, 2025). "Lung cancer patients with KEAP1 mutations present with more aggressive disease and have decreased survival rates, likely due to constitutive NRF2 pathway activation." (PMID 41462606, 2025). "STK11 and KEAP1 co-mutations with KRAS are primarily observed in lung cancer, as these two genes are rarely mutated in other cancers with high KRAS mutation rates." (PMID 40611261, 2025). "Further confirming the dependence of AIFM2 expression on STK11 and KEAP1 mutations, significantly higher levels of AIFM2 at both protein and mRNA levels were seen in lung cancer samples with STK11/KEAP1 mutations." (PMID 39995872, 2025). "Tumours with genetic activation of NRF2 are resistant to all current anti-cancer therapies, including ICIs, and therefore most lung cancer patients with mutations in KEAP1, or the NRF2 encoding NFE2L2, will progress to second-line treatment strategies." (PMID 40890297, 2025). "KEAP1 deficiency also promotes the progression of KRAS-driven lung cancer and leads to its dependence on glutamine metabolism." (PMID 40083325, 2025). "To investigate the relationship between cellular Nrf2 expression levels and resistance to ACA-28, we used the A549 human lung cancer cell line, which harbors the Keap1 mutation expressing high Nrf2 protein levels." (PMID 38500550, 2024). "Consistent in many studies, KEAP1 mutations in lung cancer result in T-cell suppression that promotes immune escape and cancer progression, a finding we also observed." (PMID 38542481, 2024). "Clinical studies have shown that the mutation frequency of Keap1 and Nrf2 is approximately 25% in lung cancer patients." (PMID 38634043, 2024).
lung carcinoma (continued). "Although gene alteration in KEAP1 or NFE2L2, encoding NRF2, are found in approximately 4 % of all cancer samples according to the cBioportal database, tumors harboring KEAP1 or NRF2 mutations are particularly higher in lung cancer (15 % or 9 %, respectively)." (PMID 38908072, 2024). "An illustrative example of such cancer types is KEAP1-mutant lung cancer, in which KEAP1 loss-of-function mutation leads to stabilized NRF2, which in turn enhances the transcription of SLC7A11 and results in its high expression." (PMID 38428031, 2024). "Lung cancers with mutations in KEAP1 (an important tumor suppressor gene) are known to be radiotherapy-resistant, which highlights the key role of SLC7A11 in radioresistance." (PMID 39029955, 2024). "Certain types of lung cancer become refractory due to specific genetic changes, such as KEAP1-mutated lung cancer, which is resistant to most current treatment methods." (PMID 39744129, 2024). "Subsequent investigations demonstrated that FSP1, regulated by Nrf2, significantly inhibited lung cancer cell growth and sensitised Keap1-deficient cells to ferroptosis by knockdown or inhibition of FSP1 expression in Keap1 post-mutant lung cancer." (PMID 39557840, 2024). "Although the preliminary analysis did not indicate the prognostic value of KEAP1 mutation, according to previous research and experience, KEAP1 mutation has been shown to have an impact on the prognosis of lung cancer patients." (PMID 38962454, 2024). "According to the TGCA database, about 14%, 11%, and 9% of lung cancer possess mutations in Kelch Like ECH Associated Protein 1 (KEAP1), Neurofibromatosis type 1 (NF1), and Epidermal growth factor receptor (EGFR), respectively." (PMID 39596025, 2024). "In contrast, methylation of the KEAP1 promoter has been found to reduce KEAP1 levels in lung cancer, a process that is associated with elevated NRF2 expression." (PMID 38671872, 2024). "KRAS, a critical oncogenic driver of lung cancer, is frequently co-mutated in lung cancers: 27% of patients with KRAS mutations also have deleterious mutations in KEAP1/NFE2L2 genes, comprised of 24% KEAP1 and 3% NFE2L2 co-mutations." (PMID 38542481, 2024). "Recently, the resistance mechanisms mediated by KEAP1 mutations have been increasingly revealed in other therapeutic approaches, especially in lung cancer." (PMID 39061847, 2024). "This is consistent with previous reports of mutations in lung cancer fitness, and it reflects the higher incidence of mutations such as KEAP1, NFE2L2, EGFR, and MYC." (PMID 38459554, 2024). "We analyzed the variant types of the NRF2/KEAP1 gene in patients with lung cancer through the c-BioPortal website [data from The Cancer Genome Atlas (TCGA) database]." (PMID 38169561, 2024). "To explore the significance of KEAP1 mutation on the prognosis of lung cancer patients, we analysed the survival of lung cancer patients with wild-type KEAP1 and KEAP1 mutations." (PMID 38962454, 2024). "Overall, the data shows that in lung cancer cells with KEAP1 R320Q and R470C mutations, increased TRAF2 and NFκB activity is essential for the anti-apoptotic protection." (PMID 38184997, 2024). "KEAP1 mutations confer worse outcomes to immunotherapy among lung cancer patients with KRAS mutation, and KEAP1 mutations results in distinct immunophenotypes in KRAS mution of lung cancer." (PMID 38884095, 2024). "Li identified ATM and KEAP1 as new targets in lung cancer, and KEAP1 deficiency sensitized lung tumors to ATM inhibition." (PMID 38347129, 2024). "In this study, we demonstrated that NRF2 activation caused by NRF2/KEAP1 mutations was associated with poor prognosis in patients with lung cancer." (PMID 38169561, 2024). "Loss-of-function mutations in KEAP1 frequently occur in lung cancer and are associated with poor prognosis and resistance to standard of care treatment, highlighting the need for the development of targeted therapies." (PMID 38536921, 2024).
lung carcinoma (continued). "In kelch-like ECH-associated protein 1 (KEAP1)-mutant lung cancers, NRF2 has been shown to promote the transcriptional expression of FSP1." (PMID 39624080, 2024). "Kelch-like ECH-associated protein 1 (Keap1), the upstream negative regulator of Nrf2 was found to control ferroptosis in lung cancer cells." (PMID 38705513, 2024). "Mutations or defects in KEAP1 in lung cancer cells result in constitutive activation of NRF2 and aberrant expression of NRF2 transcriptional targets, including SLC7A11." (PMID 39029955, 2024). "For example, somatic mutation of Keap1 in lung cancer, causing an increase in Nrf2 protein expression levels, leads to lung cancer initiation and progression." (PMID 38634043, 2024). "The prognosis of lung cancer patients with Keap1 or Nrf2 mutations is worse than that of lung cancer patients without this mutation." (PMID 38634043, 2024). "In lung cancer, alterations in the Keap1-Nrf2 pathway, such as mutations or loss of Keap1 function, are common and significantly contribute to tumor development." (PMID 39682234, 2024). "KEAP1 mutation is associated with cancer progression, treatment resistance, and poor patient survival in lung cancers." (PMID 38413563, 2024). "TRAF2 is a well-known regulator protein of TNFα-NFκB signaling, shown to be enriched in the GSEA analysis of lung cancer patients with KEAP1 mutation in sites R320 and R470." (PMID 38184997, 2024). "Intriguingly, KEAP1-mutant or KEAP1-deficient lung cancer cells exhibit an increased reliance on glucose, and under glucose-deprived conditions, they accumulate disulfide molecules aberrantly due to upregulated SLC7A11-mediated cystine uptake." (PMID 38428031, 2024). "FSP1 has also been identified as a transcriptional target of Nrf2, and acts as the key effector in Nrf2-mediated ferroptosis resistance and radioresistance in KEAP1 deficient lung cancer cells." (PMID 37714846, 2023). "In lung cancer cells, deficiency or mutations in KEAP1 result in upregulating the CoQ–FSP1 axis via NRF2, leading to resistance to ferroptosis and radiation therapy." (PMID 37371948, 2023). "Aberrations in stress signaling pathways, such as nuclear factor erythroid 2-related factor 2 (NRF2)/Kelch-like ECH-associated protein (KEAP1), shape lung cancerization, especially adenocarcinoma, and subsequent prognosis." (PMID 37305533, 2023). "The ubiquinone (CoQ)-FSP1 axis mediates ferroptosis- and radiation- resistance specifically in lung cancer cells harboring KEAP1 mutations." (PMID 36632216, 2023). "When the CoQ-FSP1 axis is inhibited, the sensitivity of KEAP1-deficient lung cancer cells and patient-derived xenograft tumors to radiation is enhanced." (PMID 37005430, 2023). "Two patients harbored a KEAP1 mutation, which has been associated with tumor progression and treatment resistance in lung cancer." (PMID 37507657, 2023). "Pharmacological inhibition of the CoQ-FSP1 axis re-sensitizes KEAP1-deficient lung cancer tumors, which are inherently resistant to radiotherapy, in part, by inducing ferroptosis." (PMID 36632216, 2023). "Keap1 and Nrf2 pathway mutations and their chemoresistance have been reported in lung cancer, as well as in head and neck cancer." (PMID 37894373, 2023). "The resulting glutamate-deficient state in lung cancers that bear KEAP1 mutations was also highlighted in another study that employed a KRAS-driven lung cancer model." (PMID 36509429, 2023). "It is ubiquinone (CoQ)-FSP1 axis that mediates ferroptosis resistance and radioresistance in KEAP1 deficient lung cancer cells." (PMID 37714846, 2023). "Our results suggest that IACS-6274 is a potent radiosensitizer for lung cancer including a radioresistant sub-population with mutations in KEAP1." (PMID 38075487, 2023).